ALB (albumin)
Diseases named in the same sentence as ALB in open-access papers (continued):
Sharing a sentence is not in itself a finding about the gene and the disease.
tumor (continued). "One study indicated that in 4T1 tumor-bearing mice, the albumin/CPT-ss-EB nano-complex exhibited efficient tumor accumulation, which subsequently contributed to outstanding therapeutic efficiency." (PMID 33925750, 2021). "Our experimental study on drug tissue distribution in vivo demonstrated that the paclitaxel palmitate albumin nanoparticles (Nab-PTX-PA) remained in the tumor for a longer time post-injection." (PMID 34109887, 2021). "Although no influence of CD3+ (P = .386) and CD8+ (P = .648) cells were found on general disease-free survival, infiltration of CD3+ (P = .012), tumor size (P = .032) and albumin (P = .007) cells independently predicted late-phase disease-free survival." (PMID 35049245, 2021). "For instance, the high concentration of albumin in the blood (40 mg/mL) compared to the interstitial concentration of 14 mg/mL aids in the diffusional transport of albumin to tumor sites." (PMID 34298666, 2021). "While groups were comparable for sex, body mass index (BMI), serum albumin, pre-procedural performance status, tumour histology, and tumour stage, the laparoscopic group were marginally younger than those undergoing open surgery (P = 0.014)." (PMID 34645433, 2021). "HGC integrates both into a preoperative staging system, by combining C-reactive protein (CRP), albumin, and disseminated tumor cells (DTC) in the bone marrow." (PMID 34885052, 2021). "Blood routine analysis showed that Nab-PTX-PA had fewer adverse effects or less toxicity to the normal organs, and it inhibited tumor cell proliferation more effectively as compared with commercial paclitaxel albumin nanoparticles." (PMID 34109887, 2021). "Albumin inhibits tumor progression by reducing excessive inflammatory responses by tumor-associated neutrophils." (PMID 34895201, 2021). "Albumin is the main component of serum proteins, and it is considered a prognostic indicator for major surgery and oncologic outcome after diverse neoplasms." (PMID 33672318, 2021). "These highlights the potential clinical significance of infigratinib‐induced cell differentiation, where tumours with higher expression of HNF4α, albumin and CYP3A4 were less proliferative, therefore reducing disease progression and improving overall survival." (PMID 33179425, 2021). "Our findings are in line with several other studies showing that the risk of EM is dependent on patient characteristics, including age as well as tumor-related features, such as albumin and β2-microglobulin levels." (PMID 34764237, 2021). "The two groups differed in many variables, including age, sex, BCLC stage, tumor size, platelets, total bilirubin, albumin, prothrombin time, and tumor markers." (PMID 34885118, 2021). "On multivariable analysis, performance status, primary tumor site, radiation dose intensity, albumin, liver metastases, and number of active tumors were all independent predictors of survival (p < 0.05 for all)." (PMID 34595844, 2021). "The final model included two independent predictors for iCSF leakage, which were lengths of tumor height (OR, 95% CI: 1.1141, 1.0485–1.1839, p = 0.0005) and albumin (OR, 95% CI: 0.8698, 0.7576–0.9986, p = 0.0477)." (PMID 34765541, 2021). "For example, the interaction of albumin molecules carrying paclitaxel with SPARC was shown to enable the increased local concentration of the drug released around the tumor cells." (PMID 34770947, 2021). "Three essential pathways, known as ‘tumor-feeding mechanisms’, corroborate the importance of albumin as a drug nanocarrier." (PMID 34684020, 2021). "FcRn is known to recycle albumin, resulting in the suppression of albumin consumption and a decrease in tumor cell growth." (PMID 33497038, 2021). "The albumin level is mainly determined by the stage of MM disease or tumor load and has prognostic significance." (PMID 34103001, 2021). "Potential effects were also observed for sex and platelet count for CL, and for sex, albumin, and tumor type for V2." (PMID 33145616, 2021).
tumor (continued). "In the current research, lengths of tumor height and albumin were identified as independent predictive factors for iCSF leakage." (PMID 34765541, 2021). "The transcytosis of albumin across the endothelium of blood vessels is achieved through the well-known gp60 pathway which promotes the albumin-bound drugs into tumor cells." (PMID 33451058, 2021). "The attachment of albumin binders follows the widely recognised principle that serum protein binding of pharmaceuticals can improve the tumour uptake of otherwise rapidly cleared molecules by expanding their circulation half-life." (PMID 34439121, 2021). "This suggests that nanoparticulate albumin-bound drug efficacy can be therapeutically improved by reprogramming nutrient signaling and enhancing macropinocytosis in tumor cells." (PMID 34452170, 2021). "We evaluated NS, BMI, body mass loss (BML) and albumin, total protein, CRP, CEA, CA19-9, lipase, amylase, tumor stage, and BC using bioelectrical impedance (BIA)." (PMID 34898583, 2021). "In vitro and in vivo experiments demonstrated that the multifunctional albumin sub-microspheres possessed superior tumor-targeting efficiency." (PMID 35011278, 2021). "In this regard, albumin nanoparticles have been used for the delivery of siRNAs to a variety of tumor cells, where the internalization can be significantly improved through transcytosis." (PMID 34298666, 2021). "Albumin is often considered the essential transport protein in the delivery of drugs to tumour cells, so the study of the binding of these proteins to target compounds can be regarded as an essential aspect of developing new substances for BNCT." (PMID 34948186, 2021). "Meanwhile, nab-paclitaxel, a nanoparticle form of paclitaxel, is known to deplete tumour stroma through interaction between albumin and SPARC." (PMID 34336679, 2021). "In HPV-positive group, the maximum tumor size, neoadjuvant chemotherapy and the body mass index (BMI) correlated significantly with C-reactive protein/albumin ratio (CAR)." (PMID 34992504, 2021). "Herein, we report on the use of albumin-based nanocarriers for the delivery of nucleic acids because of their biosafety, ease of surface modification, and tumor targeting." (PMID 34298666, 2021). "This new type of tumor-targeted multifunctional albumin-based nanoparticles by drug-induced self-assembly is a facile method without any sophisticated chemistry or materials engineering, which is promising for multimodel imaging-guided multi-therapy of cancer." (PMID 34425823, 2021). "After systemic administration, the conjugate is formed between Aldox and the circulating albumin in the blood for site-selective delivery of Dox to the tumor." (PMID 34063098, 2021). "SPARC protein binds to albumin in a similar fashion to albondin and is shown to enhance drug-bound albumin accumulation within tumorous tissues." (PMID 34445120, 2021). "On multivariable analysis, performance status, primary tumor site, radiation dose intensity, albumin, liver metastases, and number of active tumors were all independent predictors of survival." (PMID 34595844, 2021). "Previous study has demonstrated that albumin is a vital source of energy and amino acids for tumor cells, and it was increasingly absorbed by tumor cells owing to fast growth and active metabolism of tumors." (PMID 33789664, 2021). "Although the proportions of patients who received antiviral treatment were similar between the two groups, many variables, including age, tumor size, platelets, albumin, and prothrombin time, differed in the IPTW-weighted nationwide cohort." (PMID 34885118, 2021). "In conclusion, ALB, CEA, tumor location and Ki67 correlate with the risk of LNM in patients with G-NET." (PMID 33789664, 2021). "After the multivariate process, CD3+ (P = .012), tumor size (P = .032) and albumin (P = .007) were independent predictors for late-phase disease-free survival." (PMID 35049245, 2021).
tumor (continued). "Recently, several inflammation-based biomarkers (e.g., albumin, CRP, NLR and PLR) have been associated with treatment outcomes in primary operable tumours." (PMID 34056114, 2021). "The interaction between gp60 and caveolin-1, which is upregulated in many cancer types aids the vesicle formation, facilitating the accumulation of albumin in the tumor mass." (PMID 33842184, 2021). "While much of this protein content results from the death of tumor and other suspended cells, plasma-derived albumin content typically exceeds 2 g/dL, i.e., a plasma albumin content corresponding to 40% of that of whole plasma." (PMID 33834026, 2021). "The first concerns the kinetics of the transfer of a macromolecular serum albumin prodrug complex from the plasma into tumor tissues." (PMID 33419160, 2021). "For late-phase disease-free survival, tumor size (P = .076) and albumin (P = .056) showed potential predictabilities and were included in multivariate analysis with CD3+ (P = .014) and CD8+ (P = .035) cells." (PMID 35049245, 2021). "Demographic and pretreatment clinical characteristics did not significantly differ between the training and validation sets, except for a significantly lower pretreatment serum albumin level and tumor size in the validation set (P = 0.017, P=0.018)." (PMID 33967603, 2021). "The independent risk factors of post-RFA fever were younger patients, low serum albumin level, general anesthesia, larger tumors, and tumor number." (PMID 34771466, 2021). "Further, serum albumin, β2-microglobulin, and lactate dehydrogenase are recommended to assess tumor burden and disease prognosis." (PMID 33718400, 2021). "SPARK protein expression is increased in several cancers, and as a result, this property of albumin nanoparticles leads to active targeted drug delivery to tumor tissue." (PMID 34051806, 2021). "Our tree model identified 5 nodes that sub-classified the TGR by AFP, initial tumor size, and albumin." (PMID 34966854, 2021). "For example, TNF can inhibit the transcription of the albumin gene, leading to a low level of albumin in the host, which is conducive to tumor progression." (PMID 33732716, 2021). "Indocyanine green doses at 0.1 mg kg−1 did not reliably produce different uptake in tumor versus background tissue, likely because a high circulating level of unsaturated albumin diluted any tumor uptake of ICG-bound albumin." (PMID 32609570, 2020). "In contrast, nitric oxide inhibition has been shown to decrease tumor vascular permeability to albumin‐bound Evans blue dye." (PMID 32617520, 2020). "Albumin is widely used as an ideal drug delivery platform in anti-inflammatory and anticancer therapy because it accumulates at inflammation and tumor sites." (PMID 32375697, 2020). "A tumor targeting nanoplatform displaying contrast functions through photoacoustic imaging was developed by functionalizing NPs surface with human serum albumin." (PMID 32733871, 2020). "Based on visual examination of the correlations, covariates that were tested using the SCM included the continuous variables of baseline albumin, alanine aminotransferase, alkaline phosphatase, and longest tumor diameter, and the categorical variable of sex." (PMID 31768697, 2020). "Among them, ISS has been constructed which combined serum markers of tumor burden (ALB and β2-MG) with markers of aggressive tumor biology (LDH)." (PMID 32596309, 2020). "Albumin level ≥35 g/L, AFP <100 μg/L, PIVKA-II level <100 mAU/mL, and maximum tumor size <5 cm were associated with a significantly improved prognosis in univariate analysis (p<0.05)." (PMID 33112547, 2020). "Albumin and other plasma proteins accumulate in the tumor tissue and are used as energy substrates and for de novo protein synthesis." (PMID 32083092, 2020).
tumor (continued). "Herein, we developed a facile wet-chemical method to synthesize size-controllable, biodegradable, and metastable γ-phase MnS using bovine serum albumin (BSA) as a template for tumor pH-responsive T1-weighted MRI guided the integration of CDT and gas therapy." (PMID 32194812, 2020). "The tumor cells are identified by strong staining with human specific Ki67 antibody, while albumin staining is performed to characterize blood-brain-barrier disruption." (PMID 33768215, 2020). "Seventeen factors were associated with MCS in univariate analyses, among which 10 factors (age at diagnosis, sex, etiology, tumor stage, directed bilirubin, serum albumin, WBC, neutrophils, NLR, LMR) remained significant in multivariate analysis." (PMID 32145060, 2020). "The microenviromental anti-inflammatory properties of bromelain by uncoating cancer cells (depolymerizing MUC-1,fibrin and albumin) is thought to enhance tumor exposure to the host defense by increasing lymphocyte-to-tumor adhesion." (PMID 34466585, 2020). "The efficiency of the albumin-based delivery resides in its ability to enhance tumor targeting and accumulation." (PMID 35582218, 2020). "Female sex (p = 0.023), albumin (p = 0.003), tumor size (p < 0.001), beyond Milan criteria (p = 0.002) and PNI (p = 0.02) were significantly associated with poor OS in univariate analysis." (PMID 33129309, 2020). "This is shown by the facts that supplement of cells with H2S-treated albumin blunted the tumor-killing action of PX-12, and that blockade of extracellular sulfhydryl residues enhanced efficacy of PX-12." (PMID 32219063, 2020). "Liu and coworkers formulated a serum albumin-coated nanoparticle for delivery of photosensitizer chlorin e6 and honey bee venom melittin peptide to 4T1 tumor-bearing mice." (PMID 33298099, 2020). "Generally, preoperative CA125, albumin, D-dimer, and SIR markers were significantly associated with FIGO stage, residual tumor, and platinum response." (PMID 32771026, 2020). "Serum albumin has been reported to correlate with tumor necrosis because inflammatory cytokines reduce albumin synthesis." (PMID 32764671, 2020). "We also developed a nutritional model predicting OS including pN stage, tumor differentiation grade, and BMI, and a nutritional model predicting DFS including pN stage, tumor differentiation grade, and serum albumin." (PMID 33215031, 2020). "Independent risk factors of OS included Albumin-bilirubin (ALBI) grade, maximal tumor size, alpha-fetoprotein, and tumor response to initial TACE, which were used to develop a scoring system (“ASAR”)." (PMID 32487089, 2020). "Early pathological stage, total metabolic tumor volume(MTV>72.6ml), normal monocyte-to-lymphocyte ratio (MLR), lactate dehydrogenase (LDH) and serum albumin level were reported to significantly associate with better OS of PPLELC." (PMID 33064745, 2020). "Compared with commercially available albumin-prepared Pt NPs (chem-Pt NPs), we observed superior tumor targeting with the Pt NPs." (PMID 31992692, 2020). "Recently, the combination of CRP and albumin has been used to develop the Glasgow prognosis scoring system (GPS) for the study of tumor prognosis." (PMID 31965045, 2020). "Univariate analysis identified serum albumin, serum haemoglobin, site of primary tumour, presence of visceral metastases and time from diagnosis of cancer to incidence of pathological fracture as risk factors for survival after treatment." (PMID 32245389, 2020). "Some minor visual correlations were observed between the PK parameters and baseline albumin, alanine aminotransferase, alkaline phosphatase, and longest tumor diameter." (PMID 31768697, 2020). "There were significant correlations between SIMs and the albumin-bilirubin grade/Child-Turcotte-Pugh class (indicative of liver function status) and the staging system/portal vein invasion (indicative of the tumor burden)." (PMID 32455607, 2020).
tumor (continued). "The internalization of albumin through macropinocytosis and the downstream use of albumin-derived amino acids as a source of energy seems to be a unique property of cancer cells, since normal cells adjacent to a tumor lack this ability." (PMID 33195279, 2020). "In the presence of the antibody, albumin-NPs hijack circulating neutrophils which accumulate within the tumor and the photodynamic therapy suppresses tumor growth." (PMID 32630815, 2020). "Only very low levels of albumin-bound [68Ga]ABY-028 were in the tumor during the first 45 min—so low and so close to blood-rich host tissue that the tumor was hardly distinguishable." (PMID 32960353, 2020). "Compared with the traditional 2D cultured tumor cells (2D-HepG2), 3DP-HepG2 showed significantly improved expression of tumor-related genes, including ALB, AFP, CD133, IL-8, EpCAM, CD24, and β-TGF genes." (PMID 32582546, 2020). "The model confirmed the prognostic influence of the variables in the mHAP‐III model, namely tumor number, tumor size, AFP, albumin, and bilirubin, in addition to VI and cause." (PMID 31698504, 2020). "The Nab-PTX formulation eliminates the impact of Cremophor-EL on PTX pharmacokinetics and utilizes the endogenous albumin transport mechanisms to concentrate Nab-PTX in the tumor, leading to improved anti-cancer efficacy." (PMID 31858848, 2020). "Two adjacent liver samples that clustered with the tumour samples had very low levels of Albumin mRNA (0.10 and 0.37% of all reads in Albumin gene, respectively) compared to the mean Albumin mRNA level in the adjacent liver samples (6.21% ± 3.10)." (PMID 32195184, 2020). "In this study, we studied the curcumin analogue (3,4-Difluorobenzylidene Curcumin; CDF) encapsulated bovine serum albumin (BSA) nanoparticle for tumor targeting." (PMID 32438691, 2020). "PET-tracer on the other hand shows that the larger albumin molecule had longer but heterogeneous residence times within the tumor." (PMID 32967184, 2020). "Serum albumin level is inversely correlated with healthy diet and has been recognized as a sign of rapid tumour growth." (PMID 32972385, 2020). "Tumor progression can be restrained by albumin by stabilizing DNA replication and enhancing immunity response." (PMID 32375697, 2020). "The decreased levels of Hb and albumin in the presence of PDAC can be explained by the impact of the tumor’s presence on the nutritional status." (PMID 33396882, 2020). "Based on the confocal pictures taken, the bare albumin nanoparticles were able to localize within the tumor cells." (PMID 32906686, 2020). "Using albumin as a ligand for paclitaxel NPs, it has been shown to transport NPs across endothelial cells and results in accumulation of NPs in tumor sites." (PMID 33126533, 2020). "A total of 216 patients with complete information, including gender, age, clinical stage, tumor grade, T stage, platelet content, albumin content, alpha‐fetoprotein (AFP) content, as well as vascular invasion, were enrolled into the TCGA HCC cohort." (PMID 32813933, 2020). "Here we show that it can also be useful for monitoring the selective tumor uptake of the albumin-bound fluorescent dye, ICG." (PMID 32609570, 2020). "Immunotherapy seemed to speed up the recovery of serum albumin, and the improvement of hepatic functional status expresses the improvement of the tumor microenvironment." (PMID 32695663, 2020). "Serum albumin is a part of the tumor microenvironment and plays a key role in the response to immunological agents." (PMID 32695663, 2020). "E0771 tumor-bearing mice had, in general, a lower level of albumin than healthy mice from the corresponding group." (PMID 33172201, 2020). "Unlike conventional desolvation-based albumin nanoparticles, our reduced albumin nanoparticles fully release the therapeutic cargo at acidic pH as found in the tumor microenvironment and intracellular compartments such as the lysosome." (PMID 32906686, 2020).